Y_RNA (Y RNA )
Gene: Miscellaneous RNA gene on chromosome 8 (99,527,826 to 99,527,927, forward strand). Ensembl gene ENSG00000206699.
Homologues: Orthologues: chimpanzee Y_RNA (100% identical), macaque Y_RNA (96% identical). Paralogues in human: Y_RNA (87% identical), RNY3 (86% identical), Y_RNA (86% identical), Y_RNA (85% identical), Y_RNA (84% identical), RNY3P1 (83% identical), Y_RNA (83% identical), RNY3P14 (82% identical), Y_RNA (82% identical), RNY3P11 (81% identical), RNY3P16 (81% identical), Y_RNA (81% identical), and 92 more.